ZEB1 (zinc finger E-box binding homeobox 1)
Diseases named in the same sentence as ZEB1 in open-access papers (continued):
Sharing a sentence is not in itself a finding about the gene and the disease.
thyroid cancer (33 papers, 2014 to 2025). "Collectively, the current study for the first time reported that Beclin 1 knockdown caused EMT and promoted invasion of thyroid cancer cells, at least partly via stabilization of ZEB1 mRNA via upregulation of AUF1 at both transcriptional and post-transcriptional levels." (PMID 27683118, 2016). "It has been reported that ZEB1 expression is increased in anaplastic thyroid cancers (ATCs) compared to well-differentiated thyroid cancers, indicating that ZEB1 expression may be associated with progression of thyroid cancer." (PMID 27683118, 2016). "Similarly, ZEB1 expression is associated with clinicopathological features such as advanced tumor-node metastasis stage, lymph node metastasis, and distant metastasis in patients with thyroid cancer." (PMID 38388432, 2024). "Mechanistically, TUG1 appears to exert its effects through the miR-145/ZEB1 signaling pathway, highlighting its potential relevance in the prognosis and therapeutic targeting of thyroid cancer." (PMID 41150811, 2025). "FOXE1 regulates the transcription of thyroglobulin (TG), thyroperoxidase (TPO), NKX2.1, PAX8, Sodium/Iodine Symporter (NIS), and DUOX2, genes required for hormone synthesis, and also regulates PDGFA and ZEB1 in thyroid cancer." (PMID 39588344, 2024). "Jesús MB confirmed that the role of ZEB1 silencing in reducing the migration and invasion ability of thyroid cancer cells." (PMID 38693503, 2024). "Circ-VANGL1 upregulation is in favor of enhancing the metastasis of thyroid cancer cells as it affects ZEB1 expression." (PMID 38733529, 2024). "Fourth, editing of the tumor suppressor miR-200b weakened its interaction with the target gene ZEB1 in thyroid cancer, and the editing inhibitor 8-azaadenosine diminished aggressiveness of thyroid cancer cells." (PMID 35406793, 2022). "The study has indicated that miR-429 is extremely downregulated in human thyroid cancer cells, and increased miR-429 can regulate the proliferation, metastasis, and apoptosis of cancer cells via restraining the expression of ZEB1." (PMID 34966442, 2021). "We found that edited miR-200b exhibits a lower activity against its target ZEB1-3′UTR in thyroid cancer cells, likely explaining the decrease in ZEB1 expression in ADAR1-silenced cells." (PMID 32157211, 2020). "In conclusion, we have identified ZEB1 as a bona fide target of FOXE1 in thyroid cancer cells, which provides new insights into the role of FOXE1 in regulating cell migration and invasion in thyroid cancer." (PMID 31846430, 2020). "We confirmed miR-200b overediting in thyroid tumors and we showed that edited miR-200b has weakened activity against its target gene ZEB1 in thyroid cancer cells, likely explaining the reduced aggressiveness of ADAR1-silenced cells." (PMID 32157211, 2020). "Lastly, we studied the mechanism by which FOXE1 controls ZEB1 in thyroid cancer cell lines and demonstrated the involvement of ZEB1 in the regulation of EMT in thyroid cancer cells." (PMID 31846430, 2020). "Wound healing and Transwell analysis showed that ZEB1 is likely important for the migration and invasion of thyroid cancer cells, as both parameters were decreased in silenced cells." (PMID 31846430, 2020). "To test this, we assessed the activity of WT and edited miR-200b on the ZEB1 3′UTR, and their ability to inhibit ZEB1 expression, and hence invasion capacity, in thyroid cancer cells." (PMID 32157211, 2020). "EMT is induced in aggressive forms of thyroid cancer with elevated ZEB1 levels, which can promote drug resistance through EMT-dependent and EMT-independent mechanisms." (PMID 30286728, 2018). "The current study demonstrates that knockdown of Beclin1 induces EMT via stabilization of ZEB1 mRNA through upregulation of AUF1 in thyroid cancer cells." (PMID 27683118, 2016). "ABCA1-mediated EMT promotes thyroid carcinoma malignancy through the ERK/Fra-1/ZEB1 pathway." (PMID 40297807, 2025).
thyroid cancer (continued). "Similarly, the pathway involving ERK/Fra-1/ZEB1 is responsible for promoting thyroid cancer cell invasion and progression through EMT, facilitated by ABCA1." (PMID 37874419, 2023). "Similarly, as a tumor suppressor, miR-429 can directly target ZEB1 to inhibit the proliferation and induce the apoptosis of thyroid cancer cells." (PMID 35468721, 2022). "To test whether FOXE1 regulates ZEB1 abundance in human thyroid cancer cells, we silenced its expression in K1 cells, which exhibited the greatest migration and invasion ability of all the PTC lines analyzed." (PMID 31846430, 2020). "Immunohistochemistry demonstrated that most specimens demonstrated negative correlation of Beclin 1 and ZEB1 or AUF, while positive correlation of AUF1 and ZEB1 signals, further supporting increase in ZEB1 by Beclin 1 downregulation via AUF1 upregulation in thyroid cancer tissues." (PMID 27683118, 2016). "On the basis of existing literature, together with our current findings, the current study suggested that upregulation of AUF1 and ZEB1 by Beclin 1 knockdown seemed to be the mechanism by which haploinsufficiency of Beclin 1 gene might promote aggression of thyroid cancer cells." (PMID 27683118, 2016). "For example, lncRNA TUG1 is significantly upregulated in TC tissues by competitively binding to miR-145 and deregulating its inhibition of ZEB1, thereby promoting ZEB1-mediated EMT process and enhancing the proliferation and migration of thyroid cancer cells." (PMID 40530008, 2025). "Studies have shown that siRNA molecules targeting CD73 and ZEB1, in combination with RGD-coupled chitosan lactate nanoparticles, can effectively treat thyroid cancer and improve prognosis." (PMID 40530008, 2025). "In concordance with ZEB1 upregulation, expression of mesenchymal markers N-cadherin and MMP2 was increased in thyroid cancer cells subjected to heat treatment at 40°C." (PMID 38394093, 2024). "In conclusion, we have identified ZEB1 as a bona fide target of FOXE1 in thyroid cancer cells, which provides new insights into the role of FOXE1 in regulating EMT in thyroid cancer." (PMID 31846430, 2020). "Real time RT-PCR demonstrated the significant negative correlation between steady-state levels of Beclin 1and ZEB1 or AUF1, while positive correlation between AUF1 and ZEB1 in extracts from thyroid cancer tissues." (PMID 27683118, 2016). "ZEB1 activation was responsible for EMT triggered by Beclin knockdown, as knockdown of ZEB1 restored epithelial phenotype in thyroid cancer cells with Beclin 1 knockdown." (PMID 27683118, 2016). "Increased expression of Snail, Slug, Twist, ZEB1, and ZEB2 expression in thyroid cancers has been well demonstrated." (PMID 25076938, 2014). "As EMT-TFs, ZEB1 stimulates EMT to promote the progression and metastasis of thyroid cancer cells." (PMID 38733529, 2024). "TH induces EMT by transcriptionally up-regulating ZEB-1, mesenchymal genes and metalloproteinases, and inhibits the expression of E-cadherin, which further illustrates the important potential role of EMT in the development of thyroid cancer." (PMID 37773165, 2023). "The deregulated ceRNA network of the TUG1/miR-145/zinc finger E-box binding homeobox 1 (ZEB1) signaling pathway increased cell proliferation, enhanced migration capacity, and promoted EMT formation in three thyroid cancer cell lines (the ATC cell lines SW1736 and KAT18 and the FTC cell line FTC133)." (PMID 36077665, 2022). "Given the potentially crucial role of ZEB1 in EMT, we hypothesized that FOXE1 may regulate the EMT process in thyroid cancer cells, at least partly, by targeting ZEB1." (PMID 31846430, 2020). "We found that WT miR-200b directly represses ZEB1 through its 3′UTR in TPC1 and Cal62 thyroid cancer cells, as its overexpression significantly decreased the activity of a co-transfected luciferase reporter construct containing the putative miR-200b binding region in the ZEB1 3′UTR." (PMID 32157211, 2020).
thyroid cancer (continued). "By immunohistochemistry several transcription factors implicated in EMT induction, such as SLUG (SNAI2), TWIST1 and ZEB1 are all up-regulated in ATC compared to normal thyroid and well-differentiated thyroid cancers and coordinately act to repress E-cadherin (CDH1) expression." (PMID 29383121, 2017). "We also examined the expression of ZEB1 in a panel of human thyroid cancer cell lines, but we could not establish a clear correlation between ZEB1 and FOXE1 expression." (PMID 31846430, 2020). "Current studies have shown that knockdown of Beclin-1 causes thyroid cancer cells to lose their epithelial properties and acquire mesenchymal characters consistent with EMT through stabilizing ZEB1 mRNA, and there is a negative correlation between Beclin-1 and ZEB1 in thyroid cancer." (PMID 31126310, 2019). "We also found a negative correlation of Beclin 1 with AUF1 or ZEB1 in thyroid cancer tissues." (PMID 27683118, 2016).
esophageal squamous cell carcinoma (25 papers, 2014 to 2025). Esophageal squamous cell carcinoma (ESCC) is a type of esophageal carcinoma (EC) that can affect any part of the esophagus, but is usually located in the upper or middle third. "In vitro, high expression of ZEB-1 was associated with poor OS in patients with esophageal squamous cell carcinoma." (PMID 31248382, 2019). "There is evidence that miR-128-3p inhibits metastasis and EMT in esophageal squamous-cell cancer via targeting ZEB1." (PMID 35186455, 2022). "Takehiko’s group reported that the expression of the EMT inducer ZEB1 was significantly inhibited by miRNA-150, leading to the induction of mesenchymal–epithelial transition-like changes in esophageal squamous cell carcinoma." (PMID 33848981, 2021). "For example, miR-130a-5p inhibited tumor invasiveness and development in esophageal squamous cell carcinoma via negative regulation of ZEB1." (PMID 33245102, 2020). "In esophageal squamous cell carcinoma, miR-128-3p, which is lowly expressed, inhibits the migration of cancer cells through inhibiting ZEB1." (PMID 33238881, 2020). "For instance, knockdown of NOTCH3 upregulated ZEB1 expression in esophageal squamous cell carcinoma." (PMID 31019894, 2019). "For example, hsa-mir-150 was ranked third among the predicted potential associations and it has been verified to regulate the EMT-inducer ZEB1 in esophageal squamous cell carcinoma." (PMID 29416734, 2018). "Moreover, miR-128-3p limits metastasis and EMT in esophageal squamous cell cancer (ESCC) by targeting zinc finger E-box binding homeobox factor 1 (ZEB1), which is known as the EMT activator and a key factor in promoting metastasis in PC." (PMID 35186455, 2022). "Moreover, the suppressive effect of miR205 in ZEB1 expression observed in SUM159_miR205, could be associated with reduced migration and invasion, as it was also detected in MDA-MB-231, MDCK, and esophageal squamous cell carcinoma cells." (PMID 29182685, 2017). "Mechanistically, HOTAIR acted as a ceRNA for miR-130a-5p to derepress ZEB1, promoting EMT in esophageal squamous cell carcinoma (ESCC)." (PMID 35222443, 2022). "For example, in esophageal squamous cell carcinoma, miR-128-3p can inhibit epithelial-mesenchymal transition (EMT) and metastasis of cancer cells by regulating ZEB1." (PMID 35582235, 2022). "For example, studies have demonstrated that miRNA-150 targets ZEB1, an EMT inducer, in various cancers such as CRC, epithelial ovarian cancer, and esophageal squamous cell carcinoma." (PMID 33848981, 2021). "For instance, ZEB1‐activated LBX2‐AS1 interplays with HNRNPC to strengthen the stability of ZEB1 and ZEB2 and promotes esophageal squamous cell carcinoma." (PMID 32871048, 2020). "Furthermore, LBX2-AS1 that can be activated through ZEB1, accelerates migration and epithelial-mesenchymal transition in esophageal squamous cell carcinoma via interaction with HNRNPC, thereby stabilizing ZEB1 as well as ZEB2." (PMID 34552959, 2021). "Interestingly, analysis of microarray data of NOTCH3 knockdown (GSE27424) showed that silencing NOTCH3 results in a significant increase of ZEB1 and a significant decrease of IRF6 in esophageal squamous cell carcinoma." (PMID 31019894, 2019). "In esophageal squamous cell carcinoma (ESCC), SIRT7 deacetylates the promoter of E74 like ETS transcription factor 3 (ELF3), rendering it no longer able to suppress miR-144-3p, a posttranscriptional suppressor of zinc finger E-box binding homeobox 1/2 (ZEB1/2) EMT markers." (PMID 37676263, 2024). "In addition, miR-627-3p could inhibit the expression of TGFB2 and the secretion of TGF-β, which leads to the downregulation of ZEB1 and the suppression of EMT in esophageal squamous cell carcinoma." (PMID 35322735, 2022).
esophageal squamous cell carcinoma (continued). "Moreover, it has been proved that Zinc-finger E-box binding homeobox 1 (ZEB1) could induce upregulation of LBX2-AS1 to enhance the stability of ZEB1 and ZEB2, which could promote the migration and mesenchymal transformation of esophageal squamous cell carcinoma." (PMID 36313642, 2022).
pulmonary fibrosis (22 papers, 2014 to 2025). Chronic progressive interstitial lung disorder characterized by the replacement of the lung tissue by connective tissue, leading to progressive dyspnea, respiratory failure, or right heart failure. "Here we provide evidence that ZEB1-mediated EMT in human alveolar epithelial type II (ATII) cells contributes to the development of lung fibrosis by paracrine signalling to underlying fibroblasts." (PMID 30050057, 2019). "In line with this, exposure of human lung cells to nickel (Ni), an environmental and occupational pollutant linked to lung fibrosis, caused ZEB1-dependent EMT, which was irreversible even after the termination of Ni exposure." (PMID 30050057, 2019). "This study suggests that activation of EMT through HIF-1α-ZEB1 pathway is associated with progressive lung fibrosis induced by bleomycin." (PMID 26819949, 2015). "As expected, as P. agglomerans antigen-induced pulmonary fibrosis progressed, expression of Snail2, Zeb1, and Zeb2 increased in both VD3-sufficient and VD3-deficient mice, but their levels were significantly higher in animals on the restricted diet." (PMID 41465203, 2025). "Toosendanin can inhibit the ZEB1/CTBP1protein interaction and further inhibit the progression of pulmonary fibrosis." (PMID 37138491, 2024). "Our study preliminarily demonstrated the close association between ZEB1 and CTBP1 in pulmonary fibrosis on both animal and cellular levels." (PMID 37138491, 2024). "By stimulating the PI3K-AKT signaling cascade and activator of transcription in lung tissue, ZEB1 has been demonstrated to increase the progression of pulmonary fibrosis." (PMID 36824454, 2023). "Some studies identify the way in which epithelial cells regulate myofibroblast differentiation to synthesize more ECM through ZEB1 paracrine signaling in lung fibrosis." (PMID 36614217, 2023). "We next addressed how the expression of EMT-inducing transcription factors, Snai1, Snai2, Twist1, Twist2, Zeb1 and Zeb2, changed in the lungs from WT and Plaur-/- mice at Day 7, 14, 21 and 28 after bleomycin-induced pulmonary fibrosis." (PMID 36674896, 2023). "We did not only demonstrate that ZEB1/2 is a therapy target for ALI but also developed a promising siRNA delivery system for inflamed lung delivery to attenuate the progression of early pulmonary fibrosis during ALI." (PMID 35923570, 2022). "For examples, functional studies are needed to identify the role of mTOR, ROCK1, and ZEB1 in the pathogenesis of pulmonary fibrosis." (PMID 25358403, 2014). "In our study, ZEB1 was overexpressed in the alveolar epithelial cells from pulmonary fibrosis patients." (PMID 25358403, 2014). "It is speculated that CTBP1/ZEB1 may be the protein target of Toosendanin playing the role of anti-pulmonary fibrosis." (PMID 37138491, 2024). "The purpose of this study was to investigate whether CTBP1 plays a role in the proliferation and activation of pulmonary fibrosis fibroblasts through ZEB1." (PMID 37138491, 2024). "In order to investigate whether Toosendanin can play a role in the treatment of pulmonary fibrosis through CTBP1/ZEB1, fibroblast models were established in vitro." (PMID 37138491, 2024). "In addition, we found that Toosendanin plays an inhibitory role in pulmonary fibrosis by inhibiting CTBP1/ZEB1." (PMID 37138491, 2024). "Moreover, ZEB1/2 is positively correlated with the progression of early pulmonary fibrosis induced by lipopolysaccharide (LPS)." (PMID 35923570, 2022). "Therefore, ZEB1/2 can be considered novel target for the treatment of early-stage pulmonary fibrosis after ALI." (PMID 35923570, 2022). "Targeting this novel ZEB1 regulatory axis may be a viable strategy for the treatment of pulmonary fibrosis." (PMID 30050057, 2019). "Moreover, vitamin D deficiency aggravated upregulation of pulmonary ZEB1, a transcription factor for EMT, during BLM-induced lung fibrosis." (PMID 31775746, 2019).